PTS (6-pyruvoyltetrahydropterin synthase)
Description:
Involved in the biosynthesis of tetrahydrobiopterin, an essential cofactor of aromatic amino acid hydroxylases. Catalyzes the transformation of 7,8-dihydroneopterin triphosphate into 6-pyruvoyl tetrahydropterin.
Synonyms: PTPS
Tractability: Small molecule: it has a binding pocket of medium quality. PROTAC: ubiquitination databases record sites on it; its protein half-life has been measured.
Target class: Enzyme; Lyase
Gene: Protein-coding gene on chromosome 11 (112,226,367 to 112,269,955, forward strand). Ensembl gene ENSG00000150787.
Subcellular location (Human Protein Atlas): Cytosol
Pathways (Reactome):
Metabolism: Tetrahydrobiopterin (BH4) synthesis, recycling, salvage and regulation
Gene Ontology:
Molecular function: identical protein binding; protein binding; 6-pyruvoyltetrahydropterin synthase activity
Biological process: amino acid metabolic process; central nervous system development; tetrahydrobiopterin biosynthetic process
Cellular component: cytoplasm; mitochondrion; cytosol
Genetic constraint (gnomAD): Loss-of-function variants: 23 observed, 19.04 expected, observed/expected ratio (o/e) 1.21, 90% interval 0.87 to 1.7. The upper end of that interval is the gene's LOEUF score, 1.7, which puts it in group 6 of 6, group 1 being the genes least tolerant of losing a copy. Missense variants: 186 observed, 179.45 expected, observed/expected ratio (o/e) 1.04, 90% interval 0.92 to 1.17. Synonymous variants: 65 observed, 59.7 expected, observed/expected ratio (o/e) 1.09, 90% interval 0.89 to 1.34.
Gene-disease validity (ClinGen):
ClinGen rates the evidence that PTS causes each of these diseases.
BH4-deficient hyperphenylalaninemia A (autosomal recessive): Definitive. An autosomal recessive condition caused by mutation(s) in the PTS gene, encoding 6-pyruvoyl tetrahydrobiopterin synthase.
Homologues: Orthologues: chimpanzee PTS (99% identical), macaque PTS (98% identical), guinea pig PTS (85% identical), pig PTS (85% identical), rabbit PTS (85% identical), mouse Pts (81% identical), rat Pts (78% identical), tropical clawed frog pts (69% identical), zebrafish pts (58% identical), Drosophila melanogaster pr (55% identical), Caenorhabditis elegans ptps-1 (49% identical).
Diseases named in the same sentence as PTS in open-access papers:
PTS is named in the same sentence as 45 diseases in open-access papers, as found by Europe PMC text mining. Sharing a sentence is not in itself a finding about the gene and the disease. The quoted sentences say what the papers report.
DHPR deficiency (10 papers, 2015 to 2025). "The guide RNA (gRNA) was designed to target sequences in the vicinity of the c.243G > A variant in the endogenous PTS gene in PTPS deficiency or the c.176C > A variant in the endogenous QDPR gene in DHPR deficiency." (PMID 27798097, 2016). "Expanding the genes in the targeted next generation dystonia panels including SLC18A2 (VMAT2 deficiency), AADC gene (AADC deficiency), QDPR (DHPR deficiency) and PTS (PTPS deficiency) would preempt the necessity of CSF neurotransmitter metabolite measurements." (PMID 25758715, 2015). "Patients were diagnosed as follows: nine patients affected by PTPS deficiency (and identified PTS variants), two patients affected by Pterin‐four alpha‐carbinolamine dehydratase deficiency (and identified PCBD1 variants) and one patient affected by DHPR deficiency (and identified QDPR variants)." (PMID 36537053, 2023).
Hyperphenylalaninemia (7 papers, 2017 to 2025). "WES analysis has shown that neither of these patients had pathogenic, likely pathogenic, or variants of uncertain significance (VUS) above 50% posterior probability in genes associated with hyperphenylalaninemia (GCH1, PCBD1, PTS, QDPR, SPR and DNAJC12)." (PMID 40473815, 2025). "This study identified three novel mutations in either the PAH or PTS gene and supported the use of NGS as an alternative molecular genetic approach for definite diagnosis of hyperphenylalaninemia, thus leading to proper management of these patients in Thailand." (PMID 28915855, 2017). "When no PAH variants are detected in a child with hyperphenylalaninemia, the genes for the various tetrahydropterin BH4 deficiencies are tested, such as GCH1, PTS, QDPR, and PCBD1." (PMID 38132826, 2023).
phenylketonuria (3 papers, 2014 to 2022). Phenylketonuria (PKU) is the most common inborn error of amino acid metabolism and is characterized by mild to severe mental disability in untreated patients. "Genetic analysis showed that six cases carried PAH mutants and one case carried PTS mutant in patients with phenylketonuria, suggesting that mutations in PAH gene are the predominant cause of phenylketonuria in Jining." (PMID 29731766, 2018). "Pathogenic mutations in the PAH and PTS genes were detected in four and one phenylketonuria cases, respectively." (PMID 29731766, 2018). "To develop a rapid method for the diagnosis of phenylketonuria (PKU) and tetrahydrobiopterin (BH4) deficiency, we designed a multiplex, PCR-based primer panel to amplify all the exons and flanking regions (50 bp average) of six PKU-associated genes (PAH, PTS, GCH1, QDPR, PCBD1 and GFRP)." (PMID 24705691, 2014). "BH4 is sold under the brand names Kuvan and Biopten for supplementation in BH4 deficiency caused by genetic inactivity of GTP-cyclohydrolase-I (GTPCH-I) or 6-pyruvoyltetrahydropterin synthase (PTPS), both enzymes involved in BH4 synthesis as encountered in phenylketonuria." (PMID 35740082, 2022).
breast carcinoma (2 papers, 2021 to 2025).
Alzheimer disease (1 paper, 2020). A progressive, neurodegenerative disease characterized by loss of function and death of nerve cells in several areas of the brain leading to loss of cognitive function such as memory and language. "Furthermore, 6-pyruvoyltetrahydropterin synthase deficiency is a neurodegenerative disease like PD that is treated by levodopa; similarly, dihydropteridine reductase (DHPR) deficiency; the inverse Warburg effect is associated with neurodegenerative diseases like Alzheimer’s disease and PD." (PMID 32455603, 2020).
anthrax (1 paper, 2025). "In B. anthracis, deletion of PTS proteins (HPr and Enzyme I) results in decreased atxA transcription and anthrax toxin production indicating the crucial role of PTS in anthrax virulence." (PMID 39998073, 2025).
endometritis (1 paper, 2025). An acute or chronic, usually bacterial infectious process affecting the endometrium. "To explore the differences in functional features between E. coli genomes from the uterus with and without clinical endometritis, we reconstructed the PTS and ABC transporters and metabolic KEGG modules." (PMID 40431550, 2025).
lymphatic system disorder (1 paper, 2025). A disease involving the lymphatic part of lymphoid system. "In our study, AE signals associated with tirofiban were identified from two databases and were found to involve 23 SOCs and 63 PTs, primarily concentrated in the SOCs of cardiac disorders, vascular disorders, and blood and lymphatic system disorders." (PMID 41458952, 2025).
mastitis (1 paper, 2020). Inflammation of breast tissue during lactation or postpartum due to an obstructed duct or infection. "Increased PTS expression has been hypothesized to facilitate the pathogenesis of S. aureus in mastitis and may also facilitate S. aureus adaptation to secondary organs during bloodstream infection as shown in this study." (PMID 32843554, 2020).
melanoma (1 paper, 2021). A malignant, usually aggressive tumor composed of atypical, neoplastic melanocytes. "Moreover, public data from Oncomine and TCGA showed that high GCH1 expression correlates with melanoma aggressiveness, increased expression of PTS and SPR, and decreased GCHFR expression in melanoma when compared to benign nevi." (PMID 34502464, 2021).
neuroblastoma (1 paper, 2022). Neuroblastoma (NB) is the most common solid, extracranial childhood tumor. "Therefore, we subsequently analyzed the effect on splicing of both variants c.243 + 3A>G and c.164-672C>T in SH-SY5Y neuroblastoma cells, given the relevant role of the PTS gene in the central nervous system." (PMID 35833796, 2022).
infection (5 papers, 2013 to 2024). The state of being infected such as from the introduction of a foreign agent such as serum, vaccine, antigenic substance or organism. "Interestingly, several PTS-encoding genes were upregulated early or late during infection while others were downregulated such as ribose-specific PTS (CDR0303-0305)." (PMID 27351947, 2016). "Using microarrays, a transcriptional profiling of L. monocytogenes following epithelial cell infection identified several up-regulated PTS genes." (PMID 28900418, 2017). "Several genes of PTS and ABC transporters were significantly regulated during the infection, underlying the ability of strain R20291 to adapt its metabolism according to nutrient availability in the digestive tract." (PMID 27351947, 2016). "We found 9 PTS genes that formed a distinct highly expressed cluster compared to the rest of the PTS genes during infection of HeLa cells with S. Typhimurium." (PMID 24797930, 2014). "A previous report demonstrated the upexpression of PTS-EIIA and ugl during infection of the lung, indicating that utilization of HA may also contribute to bacterial growth during disease." (PMID 24171169, 2013).
PTS also shares sentences with these, for which no sentence is quoted: cancer (3 papers); Dystonia (3); GTPCH deficiency (3); microcephaly (3); Parkinsonism (3); AADC deficiency (2); deficiencies (2); Developmental delay (2); movement disorder (2); Alport syndrome (1); amino acid metabolic disease (1); and motor delay (1); Apert syndrome (1); Cerebral atrophy (1); Chorea (1); colon carcinoma (1); colorectal cancer (1); dwarfism (1); epilepsy (1); Esophageal stricture (1); genetic disorders (1); hepatitis B (1); hereditary cancer (1); Intellectual disability (1); Laryngomalacia (1); malaria (1); metabolic disorder (1); neurodegenerative disease (1); pyridoxine metabolism disorders (1); schizophrenia (1).
A further 3 diseases each share a sentence with PTS in 1 paper.